ATP1A3 (ATPase Na+/K+ transporting subunit alpha 3)
Diseases named in the same sentence as ATP1A3 in open-access papers (continued):
Sharing a sentence is not in itself a finding about the gene and the disease.
Cognitive impairment (8 papers, 2015 to 2025). Abnormal cognition is characterized by deficits in thinking, reasoning, or remembering. "These mice could thus help advance our understanding of the underlying neural mechanisms influencing cognitive impairment in patients with ATP1A3-related disorders." (PMID 26501181, 2015). "Mice carrying loss-of-function mutations in the ATP1A3 gene encoding for α3 have a reduced threshold for induction of epileptiform activity and, in humans, loss-of-function mutations in the ATP1A3 gene are associated with a variety of neurological symptoms and cognitive deficits." (PMID 30060621, 2018). "Looking for a combination of paroxysmal events, hyperkinesia, neuropsychiatric symptoms, and cognitive impairment, as well as evaluating CADD score and variant location, can aid in the diagnosis of an ATP1A3-related disorder." (PMID 36192182, 2022). "Because Myk/+ mice showed deficits in all of the tests used in the present study, we conclude that they do exhibit learning and memory deficits resembling the broadly defined cognitive impairments of patients with ATP1A3-related disorders." (PMID 26501181, 2015). "A combination of broader symptom categories, such as paroxysmal symptoms, hyperkinetic symptoms, neuropsychiatric symptoms, and cognitive impairment, has been proposed to increase sensitivity in identifying patients with ATP1A3‐related disorders than relying on restricted phenotypes." (PMID 38247386, 2024). "Patients carrying the same ATP1A3 mutation tend to exhibit similar clinical phenotypes, including not only similar motor symptoms, but also non-motor symptoms, such as cognitive impairment, psychotic disorder, and verbal fluency impairment." (PMID 35978945, 2022). "To investigate whether Myk/+ mice exhibit learning and memory deficits resembling the cognitive impairments of patients with ATP1A3-related disorders, we subjected them to a range of behavioral tests that interrogate various cognitive domains." (PMID 26501181, 2015). "Our study shows that looking for a combination of paroxysmal events, hyperkinesia, neuropsychiatric symptoms, and cognitive impairment and evaluating the CADD score and variant location can help identify an ATP1A3-related condition, rather than applying diagnostic criteria alone." (PMID 36192182, 2022).
familial hemiplegic migraine (7 papers, 2014 to 2020). A migraine disorder characterized by individual and family history of aura that includes motor weakness. "ATP1A2 and ATP1A3 have previously been implicated in familial hemiplegic migraine (OMIM 602481) and alternating hemiplegia (OMIM 614820)." (PMID 31572294, 2019). "An Italian family with familial hemiplegic migraine (FHM) with the absence of mutations in the known genes associated with this disorder, namely ATP1A2, ATP1A3, CACNA1A, and SCN1A, has recently been reported." (PMID 32549268, 2020).
Encephalopathy (6 papers, 2019 to 2026). Encephalopathy is a term that means brain disease, damage, or malfunction. "Here, we report an additional case with an ATP1A3 mutation at c.2267G>A p residue 756H presenting with fever-induced paroxysmal muscle weakness and encephalopathy." (PMID 35047275, 2021). "A new phenotype of fever-induced paroxysmal muscle weakness and encephalopathy (FIPWE) in patients with ATP1A3 mutations at c.2267G>A p residue 756H has been described most recently in few cases." (PMID 35047275, 2021).
Epileptic encephalopathy (5 papers, 2017 to 2023). A condition in which epileptiform abnormalities are believed to contribute to the progressive disturbance in cerebral function. "The authors described a patient who developed a severe early onset drug-resistant epileptic encephalopathy, and interestingly a novel mutation in ATP1A3 gene was found in this case." (PMID 36866063, 2023). "Among the ATP1A3 mutations, G358V, I363N, and E815K were related to early-onset epileptic encephalopathy." (PMID 35968298, 2022).
epileptic seizures (5 papers, 2016 to 2024). "Inactivating Atp1a3 mutation is associated with epileptic seizures since it increases the excitability of neurons." (PMID 38212833, 2024). "Seizures were found to occur in a Myshkin mouse model with I801N mutation in ATP1A3, indicating that the Na-K-ATP enzyme plays an important role in the control of epileptic electrical activity and seizures." (PMID 35968298, 2022).
auditory neuropathy (4 papers, 2017 to 2022). A hearing disorder characterized by impaired transmission of signals through the auditory nerve, resulting in mild to severe hearing loss and poor speech perception. "Auditory neuropathy with ATP1A3 mutation are generally considered to have ideal CI results." (PMID 34692702, 2021).
deafness (4 papers, 2020 to 2025). An inherited or acquired condition characterized by the complete loss of the ability to hear from one or both ears. "The most frequent causative deafness gene was TMC1 (DFNA36) (3 cases), followed by the next tier of genes (2 cases each) (CDH23, COCH, SLC26A4, TMPRSS3, ATP1A3), and the genes that were detected only once (ACTG1, GJB2, ILDR1, MYO7A, MYO15A, NF2, NLRP3 and SERPNB6)." (PMID 32238869, 2020).
ovarian carcinoma (4 papers, 2022 to 2025). A malignant neoplasm originating from the surface ovarian epithelium. "Previous studies have demonstrated a strong association between ATP1A3 expression and the progression of glioma and ovarian cancer." (PMID 41374320, 2025). "In addition, Although Wang’s study built a five-gene risk model behaving well in prognostic prediction, the role of some genes, such as UBD, ATP1A3, and HLA-DOB, remains unclear in ovarian cancer." (PMID 37095524, 2023). "At present, there is no research on the relationship between ATP1A3 and tumor, and our research shows that ATP1A3 may be involved in tumorigenesis and development as an oncogene of ovarian cancer, so above results may be a new direction for future research." (PMID 35812403, 2022).
autism (3 papers, 2020 to 2025). Persistent deficits in social interaction and communication and interaction as well as a markedly restricted repertoire of activity and interest as well as repetitive patterns of behavior. "For example, mutations in Grin1, Myh10, Mapk1, and Atp1a3 were found in autism patients or mice." (PMID 32033586, 2020).
Cerebellar atrophy (3 papers, 2016 to 2022). Cerebellar atrophy is defined as a cerebellum with initially normal structures, in a posterior fossa with normal size, which displays enlarged fissures (interfolial spaces) in comparison to the foliae secondary to loss of tissue. "Importantly, hemispheric and vermian cerebellar atrophy is severe in our patient, but in CAPOS and most other ATP1A3 cases, cranial MRIs are usually normal, with rare reports of vermian atrophy." (PMID 26990090, 2016).
colorectal cancer (3 papers, 2020 to 2025). A primary or metastatic malignant neoplasm that affects the colon or rectum. "The analysis of breast and colorectal cancers previously indicated that ATPase Na+/K+ transporting subunit alpha 3 (ATP1A3) is associated with meningiomas, and this gene also exhibits high expression levels in brain cancer datasets." (PMID 40608007, 2025). "NCEH1 and WNT10B, and ATP1A3 have been rarely reported to be associated with AD, but WNT10B has an important role in progression of colorectal cancer and hepatocellular carcinoma." (PMID 36506318, 2022). "As observed, ATP1A1 was highly expressed in Ewing’s-sarcoma, melanoma, and colorectal carcinoma, whereas ATP1A3 was highly expressed in neuroblastoma, Burkitt lymphoma, and T-lymphocytic leukemia." (PMID 32684846, 2020).
Dysarthria (3 papers, 2020 to 2024). Dysarthric speech is a general description referring to a neurological speech disorder characterized by poor articulation.
familial hemiplegic migraine type 2 (3 papers, 2014 to 2025). "This work could go on to inform novel strategies in the management of AHC, and possibly shed light on the underlying physiology of other conditions associated with mutations in ATP1A3, such as hemiplegic migraine." (PMID 36178910, 2022).
glioblastoma (3 papers, 2020 to 2022). The most malignant astrocytic tumor (WHO grade IV). "Recently, ATP1A3 has been reported to exert significant effects in various cancers, including glioblastomas, hepatomas, and medulloblastomas." (PMID 36237326, 2022). "Another study reported that activation of ATP1A3 could sensitize glioblastoma cells to temozolomide." (PMID 36237326, 2022). "They further suggested that gamabufotalin could be a potent sensitizer of temozolomide, one of the most used clinical drugs for glioblastoma, by triggering a negative feedback loop involving the sodium pump α3 subunit (ATP1A3) and aquaporin 4 to activate p38 MAPK in glioblastoma cells." (PMID 36235115, 2022).
glioma (3 papers, 2020 to 2025). A benign or malignant brain and spinal cord tumor that arises from glial cells (astrocytes, oligodendrocytes, ependymal cells). "Overall, our study indicated that functional loss of ATP1A3, induced by the point mutation Thr794Ala, could inhibit the anti‐glioma effect of CS‐6, as well as its chemosensitizing effect for TMZ." (PMID 31746080, 2020). "In addition, recent studies have confirmed that ATP1A3 activation not only enhances temozolomide sensitivity but also inhibits the proliferation of glioma cells immediately." (PMID 38022687, 2023). "Finally, by using transfected U87 or U251 cells with ATP1A3 knockdown, we further performed cell viability assays to examine the effect of ATP1A3 on the anti‐glioma efficacy of CS‐6, as well as the synergistic therapeutic effect of CS‐6 and TMZ." (PMID 31746080, 2020). "In summary, we found that ATP1A3 might be a potential target of CS‐6 in GBM and that regulating ATP1A3 could significantly impact the anti‐glioma efficacy of CS‐6 and its combination with TMZ." (PMID 31746080, 2020).
hepatocellular carcinoma (3 papers, 2020 to 2022). A malignant tumor that arises from hepatocytes. "It has been reported that bufalin inhibits the growth of hepatocellular carcinoma (HCC) cells, which is correlated with the expression level of ATP1A3 in HCC cells." (PMID 36237326, 2022).
infantile epileptic encephalopathy (3 papers, 2023 to 2024). an epileptic condition characterized by epileptiform abnormalities associated with progressive cerebral dysfunction. "Previous research has linked ATP1A3 mutations to the most severe form of infantile epileptic encephalopathy, characterized by seizures beginning at infancy, episodic apnea, poor survival, and profound developmental retardation." (PMID 36866063, 2023).
Onset (3 papers, 2021 to 2023). The age group in which disease manifestations appear. "The disease causing missense variants in ATP1A3 was first identified in families with rapid‐onset dystonia parkinsonism in 2004, and since then several ATP1A3‐related disorders have been recognized." (PMID 32895939, 2021).
status epilepticus (3 papers, 2013 to 2023). Status epilepticus is defined as a continuous seizure lasting more than 30 min, or two or more seizures without full recovery of consciousness between any of them. "The authors reported that the E815K mutation of ATP1A3 found in half of their patients was associated with the presence of severe neurological symptoms, status epilepticus and resistance to medications." (PMID 36866063, 2023). "Intriguingly, E815K mutation of ATP1A3 found in half of our patients was associated with the presence of severe neurological symptoms, respiratory failure, status epilepticus and resistance to medications." (PMID 23409136, 2013). "Odds ratio for occurrence of status epilepticus in AHC patients with different ATP1A3 mutations." (PMID 25996915, 2015). "Finally, patients with E815K mutation were almost 3 times more likely to present with status epilepticus during the course of the disease than the patients with other types of ATP1A3 mutations (P-value = 0.0206." (PMID 25996915, 2015).
autonomic dysfunction (2 papers, 2024). "In particular, cold temperatures might become a critical factor for not only exaggerating neurological symptoms, but also provoking autonomic dysfunction and sudden death in patients with ATP1A3-related diseases." (PMID 38804677, 2024).
behavioral disorders (2 papers, 2021). "Genes linked to congenital and behavioral disorders included dynein axonemal intermediate chain 1, Rho GTPase Activating Protein 36, ATPase Na+/K+ Transporting Subunit Alpha 3 and 5-Hydroxytryptamine Receptor 2C while genes related to fitness effects include genes such as Cysteine-Three-Histidine." (PMID 34209092, 2021).
channelopathies (2 papers, 2023 to 2024). "Genetic mutations in KCNA1, CACNA1A, CACNB4, SLC1A3, SCN8A, KCNMA1, and ATP1A3 genes that encode ion channels lend support to the channelopathy theory." (PMID 37008993, 2023).
Chorea (2 papers, 2021 to 2022). Chorea (Greek for 'dance') refers to widespread arrhythmic involuntary movements of a forcible, jerky and restless fashion. "In the remaining patients, gait dystonia was associated with chorea (ATP1A3, GNAO1, and NKX2." (PMID 36054588, 2022).
congenital hydrocephalus (2 papers, 2019 to 2022). Hydrocephalus that is present at birth. "Atp1a3 deficiency in zebrafish results in hydrocephalus; however, no known association exists between ATP1A3 and human congenital hydrocephalus (CH)." (PMID 31616254, 2019).
generalized dystonia (2 papers, 2020 to 2024). "Similar to my patient, episodes of paroxysmal generalized dystonia were triggered by premenstrual periods in a patient with a different ATP1A3 mutation (p.Gly867Asp)." (PMID 39712145, 2024). "A 12 year old boy with a novel, de novo, ATP1A3 mutation had onset of dysphagia and dysarthria followed by severe generalized dystonia resulting in inability to walk." (PMID 33488508, 2020).
melanoma (2 papers, 2016 to 2020). A malignant, usually aggressive tumor composed of atypical, neoplastic melanocytes. "By microarray analysis we detected little or no expression of ATP1A2, ATP1A3 or ATP1A4 in xenografted melanomas or in normal human melanocytes." (PMID 27545456, 2016).
myoclonus dystonia (2 papers, 2021 to 2022). "Thirteen studies explored genetically homogeneous cohorts, involving DYT1 (TorsinA mutation) (n = 3) and DYT6 (THAP1 mutation) (n = 1, or both n = 2), DYT3 (n = 2), X‐linked dystonia parkinsonism (DYT12, ATP1A3 mutation, n = 2), myoclonus dystonia (DYT11, SGCE mutation, n = 2) and DYT27 (n = 1)." (PMID 35785410, 2022).
Obesity (2 papers, 2023 to 2025). Accumulation of substantial excess body fat. "However, four of the 24 common microglial DEGs were regulated in opposite directions by obesity in males and females (Unc13a, Atp1a3, and Arhgap33 upregulated in females and downregulated in males; Rbm47 upregulated in males and downregulated in females)." (PMID 41310161, 2025). "We looked for common genes between the up-DPpGCs in TS and TA, and the significant differentially expressed genes (DEGs) induced by exercise in SkM of old mice, and found four genes, ATP1A3, SLC17A7, SYN2, and COL24A1 from the up-DPpGCs in TS, that are related to neurotransmission and obesity." (PMID 36769072, 2023).
paroxysmal dystonia (2 papers, 2021 to 2024). "Video documentation of ATP1A3-associated paroxysmal dystonia has been limited." (PMID 39712145, 2024). "Paroxysmal dystonia can occur in AHC irrespective of underlying mutation in ATP1A3, including the three most common mutations (D801N, E815K, and G947R)." (PMID 33833732, 2021).
schizophrenia (2 papers, 2022 to 2023). A major psychotic disorder characterized by abnormalities in the perception or expression of reality. "Two pathogenic de novo variants in ATP1A3 and missense variants in FXYD gene family (FXYD1, FXYD2) were also identified in 17 sporadic cases of childhood onset schizophrenia using whole exome sequencing." (PMID 36384485, 2022).
Tremor (2 papers, 2021 to 2024). An unintentional, oscillating to-and-fro muscle movement about a joint axis. "Wild types commenced grooming quickly, but Atp1a3+/D801Y mice had a prolonged recovery with severe tremor and strikingly abnormal postures." (PMID 39111836, 2024). "Significantly, forced swimming resulted in delayed recovery, abnormal limb positions, and severe tremor in Atp1a3+/D801Y mice." (PMID 39111836, 2024).
adrenocortical carcinoma (1 paper, 2020). "ATP1A3 expression was significantly higher in adrenocortical carcinoma (p < 0.001), THYM (p < 0.001) and pheochromocytoma and paraganglioma (p < 0.01) than in the adjacent normal tissues." (PMID 32684846, 2020).
aldosterone-secreting adenomas (1 paper, 2016). "A gain of function such as development of a leak current is possible but has not yet been demonstrated for ATP1A3, although somatic mutations in ATP1A1 found in aldosterone-secreting adenomas induced significant leak currents." (PMID 26990090, 2016).
Anxiety (1 paper, 2024). Intense feelings of nervousness, tension, or panic often arise in response to interpersonal stresses. "Tests of anxiety in various Atp1a3 mouse strains, such as the elevated plus maze or center avoidance, have shown reduced, rather than elevated, levels." (PMID 39111836, 2024).
Baraitser-Winter syndrome (1 paper, 2025). "Loss-of-function variants in NIPBL cause Cornelia de Lange syndrome; missense variants in ACTG1 lead to Baraitser-Winter syndrome; missense variants in ATP1A3 underlie Snijders Blok-Campeau syndrome; and loss-of-function variants in TCF4 result in Pitt-Hopkins syndrome." (PMID 41300846, 2025).
breast tumors (1 paper, 2022). "In turn, present results suggest that the treatment of patients with OU or possibly other CGs could be pursued only after the molecular characterization of breast tumors has evidenced a high expression of ATP1A3 and a low expression of ATP1A1 and ATP1B1." (PMID 36232400, 2022).
bronchopneumonia (1 paper, 2020). Acute inflammation of the walls of the terminal bronchioles that spreads into the peribronchial alveoli and alveolar ducts. "In the present study, we confirmed the expression of ATP1A3 in the structurally and histologically normal heart of an adult man who died of bronchopneumonia and had postmortem examination." (PMID 32913013, 2020). "Immunolabeling for ATP1A3 was performed in an adult human heart from a 75-year-old man who died of bronchopneumonia." (PMID 32913013, 2020).
cardiac arrhythmia (1 paper, 2020). Any disturbances of the normal rhythmic beating of the heart or MYOCARDIAL CONTRACTION. "Further prospective studies of cardiac disturbances in ATP1A3-related conditions to test the utility and cost-effectiveness of this approach and to identify potential precipitating factors for life-threatening cardiac arrhythmias are warranted." (PMID 32913013, 2020).
cervical carcinoma (1 paper, 2022). A carcinoma arising from either the exocervical squamous epithelium or the endocervical glandular epithelium. "Additionally, a previous study has demonstrated that downregulation of the expression of sodium pump α1 (ATP1A1) and α3 (ATP1A3) subunits is linked to arenobufagin-triggered cytotoxicity in cervical carcinoma Hela cells." (PMID 36235115, 2022).
cervical dystonia (1 paper, 2022).